IL2 (interleukin 2)
Diseases named in the same sentence as IL2 in open-access papers (continued):
Sharing a sentence is not in itself a finding about the gene and the disease.
tumor (continued). "IL-2 may not be the predominant cytokine in a suppressed tumor microenvironment that may be skewed more toward a Th2 or suppressive environment driven by IL-10 and TGFβ." (PMID 32040476, 2020). "Furthermore, significant amelioration of the tumor in rats treated with HSP70/Il-2-treated NK cells as compared to those subjected to nontreated NK cells, as confirmed by MRI, proved the efficacy of adoptive NK cell therapy." (PMID 32218162, 2020). "These activated DCs promoted significant tumor extinction or no tumor formation in the prophylactic assay, but they failed to retard tumor growth in the therapeutic regimen, which was partially recovered in combination with IL-2 exogenous administration." (PMID 32178288, 2020). "Based on this data, we hypothesize that activation of these tumor promoting genes and increased expression of MMP2 and TGF-β1 proteins in hADSCs-IL2 could have adverse effects on tumor growth when used for the treatment of cancer patients and requires additional investigation." (PMID 32560387, 2020). "The levels of IFN-γ, IL-2 and IL-4 did not correlate with tumor cells viability." (PMID 33312693, 2020). "Splenic NK cells were purified by negative selection, activated with IL-2 (100 U/ml) for 72 h, and assessed for functional phenotype by means of their activating receptors by flow cytometric analysis and additionally, cytotoxicity towards tumor targets." (PMID 32040476, 2020). "MPE-resident CD8+ T cells were bead-isolated, rested for 24 h in complete media supplemented with 6000 IU/mL IL-2, and subsequently co-cultured for 24 h at a 1:1 ratio with either autologous tumor containing non-hematopoietic cells from the MPE or autologous peripheral blood monocytes." (PMID 32867034, 2020). "Thus it is possible that low levels of the cytokine IL-2 and high levels of angiogenic mediators - Ang-2 and bFGF, in TCM of tumour biopsies may confer a more DC inhibitory environment and this fits with some expected roles for these mediators." (PMID 32552799, 2020). "Because administration of systemic IL-2 and neutralization of TGF-β or Treg depletion through anti-CD25 was shown to augment tumor survival in a CD8 T cell and/or NK cell dependent manner, the use of this immunotherapeutic regimen may also result in similar effects following HSCT." (PMID 33138229, 2020). "Tumor cells compete with T cells for nutrients in the TME due to their similar metabolic processes, resulting in compromised T-cell receptor (TCR) signaling and dampened production of cytokines such as interferon-γ (IFN-γ), interleukin-2 (IL-2), and tumor necrosis factor-α (TNF-α)." (PMID 32424240, 2020). "During this period, lymphodepleting regimen eradicates homeostatic cytokine sinks, such as IL-7, IL-2, and IL-15, eliminates unwanted immunosuppressive cells, such as regulatory T cells and myeloid-derived suppressor cells and downregulates indoleamine 2,3-dioxygenase (IDO) in tumor cells." (PMID 32391013, 2020). "In addition, Th9 CAR-T cells secreted lower amounts of IL2 and TNF-α than Th1 CAR-T cells, but Tc9 CAR-T cells secreted significantly higher levels of IL2 and TNF-α than Tc1 CAR-T cells, especially after coculture with tumor cells." (PMID 33214555, 2020). "A rational approach is to use tumor-localized implants loaded with tumor-specific lymphocytes that contain additional T cell-activating biologicals (such as activating anti-CD3, anti-CD28, and anti-CD137 antibodies) and T cell stimulatory cytokines (like IL-2 or IL-15)." (PMID 32942725, 2020). "Interestingly, at the low E:T ratio of 0.5:1, only IL-2/IL-12/IL-18-pretreated γδ T cells exhibited a sustained anti-tumor effect, in fact irrespective of a simultaneous TCR stimulus." (PMID 31947966, 2020).
tumor (continued). "Intralesional therapies, such as T-VEC, BCG, PV-10, and IL2 can promote neoantigen exposure (through viral antigens, HMB-PP, HMGB1 proteins, and melan-A, respectively), possibly turning weakly immunogenic tumors into strongly immunogenic tumors and promoting anti-tumor immunity." (PMID 32455916, 2020). "The higher levels of IL-2 observed in disease-free patients can contribute to make the effect of NATC more stable by promoting the recruitment and activation of natural killer (NK) and cytotoxic CD8+ T lymphocytes at the tumor site, improving the ADCC mediated by trastuzumab." (PMID 32013102, 2020). "Thus, we infused non-expanded autologous TALs along with weekly IL2 support into 099-CL-Luc tumor-bearing N-HSGM3 mice and tested therapeutic efficacy either alone or in combination with ICB." (PMID 33177175, 2020). "They found that a combined protocol of starting with 10–120 IU/ml IL-2 during the first week, followed by increasing IL-2 concentration to 6000 IU/mL within the second week, results in the generation of T cells that expand well, maximally produce IFN-γ and are highly cytotoxic against tumor cells." (PMID 32391013, 2020). "The release of IL-2 and IFN-γ amplifies the immune response as IL-2 functions in delivering signals for activation, maturation, and differentiation of T-cells, B-cells and NK cells while IFN-γ recruits and activates more NK cells to the tumour microenvironment." (PMID 32612457, 2020). "Neutrophilia provide a favorable tumor microenvironment for cancer progression by secreting many inflammation mediators such as tumor necrosis factor alpha (TNF-α), vascular endothelia growth factor (VEGF), interleukin-2 (IL-2), interleukin-6 (IL-6), and interleukin-10 (IL-10)." (PMID 32911724, 2020). "However, it has to be considered that the biodistribution experiments evaluated the quantity of immunocytokine at the tumor site and not the quantity of IL2." (PMID 33110477, 2020). "Some newly developed fusion proteins that comprise IL-2 and IL-2Rα, such as ALKS 4230, could selectively active the effector cells bearing intermediate receptors, and exhibit superior tumor control efficacy and less toxicity in mouse tumor models." (PMID 33266177, 2020). "While these observations are not conclusive, the modulation of tumour permissive IL17 along with other cytokines (IL2/IL21), which stimulate T cell proliferation, supports a significant contribution of immune-based mechanisms to the clinical efficacy of this regimen." (PMID 32704173, 2020). "Since IL-2 stimulates cytotoxic T cell expansion and activation as well as that of immune suppressive regulatory T cells, it remains to be determined how the IL-2 responsiveness of DUSP6 plays into its apparent effect on immune suppression, and how this relates to tumor immune response." (PMID 30941033, 2019). "However, sequencing data from online databases show that IL-2 is not expressed or expressed in extremely low concentrations in tumor tissue." (PMID 31462678, 2019). "The B16F10 tumor growth could not be controlled by a low-dose-injection of commercial free IL-2 that was applied every other day for a total of three injections." (PMID 31462678, 2019). "Given the ability of IL‐15 and IL‐7 to act as surrogates for the absence of IL‐2 signalling, it would also be interesting to determine whether these cytokines play a role in Treg cell maintenance in tumours." (PMID 31032905, 2019). "Neither H460 nor A549 tumor growth was remarkably affected by IL-2 treatment alone." (PMID 30670085, 2019). "The lack of strong and specific tracer accumulation in the tumors led us to hypothesize that IL-2 secreted by RT-induced effector cells may compete with therapeutic IL-2c (and the 64Cu-NOTA-IL-2c tracer) for binding to CD122/γc receptors in the tumor microenvironment." (PMID 30808414, 2019). "We first tested the function of F42A mutant IL-2; the data showed that F42A mutant IL-2 could not effectively control tumor growth." (PMID 31462678, 2019).
tumor (continued). "Crucial to the generation of Treg cells are IL-2 and TGF-β, the latter particularly important as it directly induces the expression of FOXP3 (the master “identity factor” of Treg cells) via Smad factors binding to FOXP3 promoter, both of which abound in the tumor milieu." (PMID 30959898, 2019). "In another study, rNDV expressing IL-2 and tumor necrosis factor-related apoptosis inducing ligand (TRAIL) significantly enhanced inherent anti-neoplastic activity by inducing apoptosis and induced proliferation of CD4+ and CD8+ in mice also providing substantial reduction in tumor development." (PMID 30832256, 2019). "By contrast, no tumor staining and no tumor uptake could be observed for the IL2-KSF-TNFmut negative control protein." (PMID 31799191, 2019). "In addition, sumIL-2-Fc induced a significant higher number of CD8+ T cells in tumor tissue than WT IL2-Fc, and did not result in more Tregs." (PMID 31462678, 2019). "Similarly, NK cells cultured in the absence of tumour cells for 18 h and then provided IL2 for 18 h did not produce IFNγ." (PMID 31595191, 2019). "Using CD3+/CD28+ T cells isolated from immune competent mice, we observed that NextA did not induce major changes in the production of either IFNγ and IL2, implying that the anti-tumor activity of HDAC6i was not mediated by the direct action of this drug on T cells." (PMID 30992475, 2019). "Altogether, these data demonstrate that a lack of IL-2 might contribute to limited CTL responses in the tumor." (PMID 31462678, 2019). "It has been shown that BCG-stimulated PBMCs induce death of tumor cell lines through a complex mechanism involving the activation of macrophages and CD4+ T cells, which leads to the generation of BCG-activated killer cells (BAK cells - CD8+ T cells) stimulated by IL-2 and IFN-γ." (PMID 31297119, 2019). "Tumour interacting NK cells did not produce IFNγ in the absence of IL2." (PMID 31595191, 2019). "The intratumoral injection of low-dose WT IL2-Fc could not control tumor growth, but the same molar of sumIL-2-Fc effectively inhibited tumor growth." (PMID 31462678, 2019). "That is, CD4+ T cell IL-2 production in the presence of SMG E.G7 remained significantly less (p ≤ 0.02) than cytokine production by the T cells activated in the absence of the tumor." (PMID 31602007, 2019). "To understand how stimuli from tumour cells and IL2 from local T cells might affect NK cells responses, we explored NK cell responses when co-cultured with tumour cells in the presence or absence of exogenously supplied IL2." (PMID 31595191, 2019). "In 3 of the 4 tumours considered negative by 99mTc-IL2 scintigraphy, the level of CD25+ TIL was less than 15% suggesting that the low number of TIL may have been insufficient for discrimination of the T/B ratio by 99mTc-IL2 imaging." (PMID 31091813, 2019). "To determine the relative roles of T-cells and NK cells and evaluate cytokine/chemokine levels over time during anti-CD137/IL-2-Fc therapy, we depleted CD8+ T-cells or NK cells from C57Bl/6 mice bearing B16F10 tumors, then began systemic anti-CD137/IL2-Fc therapy on day 8 after tumor inoculation." (PMID 29295974, 2018). "Therefore, the omission of exogenous IL-2 is not likely the primary factor accounting for the suboptimal anti-tumor response in this study." (PMID 29980239, 2018). "Importantly, IL-2/CD40 reduced expression of a number of regulatory markers on young and elderly TDLN CD11c+ cells including: CD73, TGF-β, CD39 and IL-10, relative to age-matched untreated tumor-bearing mice." (PMID 30560130, 2018). "PBL without IL-2 did not lyse these tumor cells (data not shown)." (PMID 29725336, 2018).
tumor (continued). "Further, a significant increase of Il2 and Ifng gene expression was also observed in all treated groups; IL-2 and IFN-γ are key cytokines to develop effective immune responses, and the tumor-infiltrating CD4+ T cells are most likely one of the source of these cytokines." (PMID 29410666, 2018). "Furthermore, when activated human T cells were co-cultured with PD-L1 positive human tumor cells, PD1-Fc- OX40L was observed to concentrate within the immune synapse, which enhanced proliferation of T cells and production of IL-2, IFNγ and TNFα; leading to efficient killing of tumor cells." (PMID 30400822, 2018). "This suggests that whilst IL-2/CD40 reduces tumor-induced suppressive TDLN CD11c+ cells, it does not overcome the age-related increase in suppressive CD11c+ cells, which may be a contributing factor to the reduced efficacy of IL-2/CD40 in elderly mice." (PMID 30560130, 2018). "Furthermore, in vitro studies showed that elderly derived IL-2/anti-CD40-activated macrophages could restore age- and tumor-related T cell function." (PMID 30459812, 2018). "IL-2 may be provided by host CD4 T cells activated by homeostatic proliferation in tumor-bearing non-lethally irradiated mice." (PMID 30546366, 2018). "In addition, we tested the effect of IL-2 (a required growth factor for culturing T lymphocytes) on tumor cells, but no facilitating effect was observed either." (PMID 29350274, 2018). "Interestingly, we observed a significant negative correlation between tumor size and local IL-2 levels in tumor samples (r2 = –0.75, p = 0.0008), suggesting a positive role for this cytokine to treat tumors." (PMID 30687269, 2018). "Although mice injected with high viral titers (1012 rAAV IL-2) died within 2 weeks, mice injected with lower titer (109–1011 rAAV-IL-2) lived normal life spans with unaffected vaccine-mediated antibody responses, infection-induced immune responses, and notably, not-enhanced tumor growth." (PMID 29755456, 2018). "CXCL10 is expressed in OC TAMs as well as in peritoneal macrophages from tumor-free patients, while IL2 is not a transcribed gene in macrophages and hence is devoid of active marks but apparently harbors H3K4me3- and H3K4me1-modified nucleosomes within 2,000 bp of its TSS." (PMID 29997615, 2018). "The data revealed a trend that those patients whose NK cells preferentially responded to IL-2 stimulation, thereby enhancing their ability to lyse PC3 cells, tended to down-regulate more NKp46 than the NK cells from patients that preferentially responded to tumor priming." (PMID 30761160, 2018). "Our data demonstrate that chronic TGFβ imprinting in conjunction with activation and IL-2 has opposite effects of acute TGFβ exposure (6 h to 3 days), driving NK cells to produce more IFNγ and TNFα upon tumor target and PHA stimulation than NK cells that were not TGFβ imprinted." (PMID 30400618, 2018). "IL-2, IL-15 and IL-15 expanded TIL from primary solid cancer and metastatic lesions promotes the cultivation of a focused T-cell product directed against the patient’s autologous tumor cells and offers a viable treatment modality for patients with solid cancer." (PMID 30400835, 2018). "Indeed, a role for Treg cells in modulating tumor-specific effector T lymphocytes by producing immunosuppressive cytokines, such as IL-10 and TGF-β, consuming IL-2 or expressing the inhibitory molecule cytotoxic T-lymphocyte associated antigen (CTLA)-4, has been reported." (PMID 29403496, 2018). "Briefly, during the experiment, dCAR-T cells could release significant levels of cytokines only in the presence of cognate tumor cells expressing both CEA and MSLN, including 751 pg/mL IL-2, 9297 pg/mL IFNγ, 1777 pg/mL TNFα, 732 pg/mL IL-4, 8991 pg/mL IL-13, and 99 pg/mL IL-15." (PMID 30103775, 2018).
tumor (continued). "We demonstrate here that co-transferring less differentiated CD4+ Th1 cells and CD8+ CTLs without lymphodepletion and IL-2 administration enhances complete tumour remission and also results in generation of an endogenous memory response to non-ACT target epitopes." (PMID 29114389, 2017). "Th1 cells usually create a large quantity of interleukin-2 (IL-2) and interferon-γ (IFN-γ) which are vital for macrophage activation leading to enhancement of microbial killing and function under cell mediated immunity to destroy the intracellular viruses and tumor cells." (PMID 29201111, 2017). "The HRG fusion proteins involving IL-2 or CD3 create an interface between the HRG/HER pathway and the immune system, building the foundation for combinations with checkpoint inhibitors and better understanding of the role of HRG signaling in the anti-tumor immune response." (PMID 29179520, 2017). "Of note, only 1 of the 5 mice in the IL-2 group was cured of tumor (no visible tumor 42 days after injection), whereas in the IL/15/21 group, four of the five mice were cured and all five mice were cured of tumor in the IL-21, IL-2/21 and IL-7/15 groups." (PMID 28146052, 2017). "In contrast in KIRC with lower response to high-dose IL-2 and lower PD-L1 mRNA expression, the weak immune response may attribute to the lack of tumor-specific antigens on tumor cells and the secretion of immunosuppressive cytokines such as VEGF and TGF-β." (PMID 27926518, 2017). "Compared with control groups, exendin-4 suppressed subcutaneous tumor growth in a dose-dependent manner, accompanied by increased interferon (IFN)-γ secreting CD8+ cytotoxic T lymphocyte (CTL)/Foxp3+ regulatory T cell (Treg) ratio as well as Th1 proinflammatory cytokines IFN-γ and IL-2." (PMID 28496193, 2017). "However, in mice, CD8 αβ T cells expanded ex vivo using IL-15 or IL-7/IL-15 rather than IL-2, mediate increased tumor immunity." (PMID 28239463, 2017). "PSP also slowed the tumor progression of these mice, although not as effectively as IL-2 alone." (PMID 28932226, 2017). "Instead, the stabilized IL-2–anti-IL-2 complex preferentially acts on cells with a high level of IL-2Rβ-γc intermediate-affinity receptors, such as NK and CD8+ T cells, inducing their proliferation and STAT phosphorylation, decreasing TIL markers of “exhaustion”, and improving anti-tumor responses." (PMID 29123649, 2017). "Consequently, the conjugated-IL2 species occupy the IL2Rβγ more readily than IL2Rαβγ and this property is an inherent feature of NKTR-214 that promotes its favorable biological and therapeutic effects in murine tumor models." (PMID 28678791, 2017). "However, adoptive transfer of Vγ2Vδ2 T cells expanded with IL-15 did not result in improved tumor immunity compared to those expanded with IL-2." (PMID 28239463, 2017). "We did not treat the mice with systemic IL-2 to maintain the proliferation of CAR T cells to avoid the bias that this molecule could exert on the tumor growth." (PMID 27145284, 2016). "However, α-CD137 combined with α-PD-1 antibodies significantly enhanced the anti-tumor effect of SBRT, while the anti-tumor effect of SBRT was not enhanced by interleukin-2, or the combination of α-CTLA-4 and α-PD-1." (PMID 27160390, 2016). "However, NK cells, but not T cells, were found to kill membrane Hsp70+ tumor cells after preactivation with naturally occurring Hsp70 or an Hsp70–peptide (TKD) derived thereof in combination with low dose IL-2 (TKD/IL-2)." (PMID 27199993, 2016). "Therefore, both IL-2 and IFN-γ have direct inhibitory effects on tumour cells." (PMID 27293315, 2016). "However, in the LSPS-treated groups, the production of TNF-α and IL-2 was enhanced, indicating that LSPS administration could improve immune function in H22 tumor-bearing mice by promoting TNF-α and IL-2 production." (PMID 27827862, 2016).